ANXA2 (annexin A2)
Diseases named in the same sentence as ANXA2 in open-access papers (continued):
Sharing a sentence is not in itself a finding about the gene and the disease.
tumor (continued). "Furthermore, ANXA2 interacts with diverse signaling molecules to drive tumour progression." (PMID 40234383, 2025). "Additionally, NASP may activate the STAT3 pathway through p‐ANXA2, which, in turn, promotes radioresistance and tumor progression." (PMID 38605477, 2024). "Since ANXA2 has been shown to be a vital part of specific molecular pathways characteristic of tumors’ molecular signatures, further could eventually improve the diagnosis, prognosis, and treatment of many neoplasms of the DS." (PMID 39594718, 2024). "In RCC, ANXA2 could regulate Hippo signaling pathway, and promote migration of tumor cells." (PMID 38519766, 2024). "Furthermore, it is possible to detect elevated levels of ANXA2 in plasma EVs that are linked to non-endometrioid tumours and tumours with a high likelihood of recurrence." (PMID 39492906, 2024). "This study may provide new insights into the application of ANXA2 in tumor immunotherapy." (PMID 36713082, 2023). "Overall, Annexin A2 is effective on the host-parasite interaction of various parasites, and its interactions with other proteins and signaling pathways provide important insights into the mechanisms of parasite invasion, inhibition of tumour growth, and apoptosis induction." (PMID 37482693, 2023). "Furthermore, JICD1-driven propagation and tumor aggressiveness were inhibited by ANXA2 knockdown." (PMID 37834227, 2023). "Finally, we show that a monoclonal anti-ANXA2 antibody interferes with the function of ANXA2 in membrane repair of cancer cells, suggesting that it may constitute a relevant tool to inhibit tumor invasion and metastasis." (PMID 38092984, 2023). "Besides, ANXA2 has been found to be intracellularly and extracellularly overexpressed in various types of tumors, in which ANXA2 translocates to the tumor cell membrane and facilitates the generation of plasmin in the extracellular matrix, resulting in enhanced cancer cell invasion and migration." (PMID 36453020, 2023). "Indeed, ANXA2 may constitute an independent prognostic marker and may interact with other proteins to influence tumor recurrence, progression and metastasis." (PMID 36916296, 2023). "Furthermore, overexpression of ANXA2 in certain tumor is correlated with worst clinical outcomes and also it has been associated with a variety of oncogenic functions, including signal transduction, cytoskeletal rearrangement, membrane fusion, cellular migration, adhesion, and proliferation." (PMID 36224238, 2022). "With respect to malignancies, AnxA2 is expressed abundantly in various types of tumours where it is described to play a critical role in epithelial-mesenchymal transition, cytoskeleton dynamics and tumour cell motility, to regulate cell cycle and proliferation and to promote tumour angiogenesis." (PMID 36123610, 2022). "However, the downregulation of ANXA2 by CuO NPs might prevent tumor progression and angiogenesis via inhibition of macrophage activation and secretion of IL-1, IL-6, and TNF-α." (PMID 36362054, 2022). "In addition, ANXA2 may act as a potential marker of immunosuppression to regulate the infiltration of tumor-related macrophages, regulatory T cells, and myeloid-derived suppressor cells." (PMID 35977942, 2022). "Therefore, ANXA2 probably exerts an oncogenic role in various tumor types, and ubiquitination of ANXA2 might be a critical regulatory process in tumorigenesis." (PMID 35977942, 2022). "So, in the early stage of tumor starvation, ANXA2 may support starving cells by inducing autophagy." (PMID 36247003, 2022). "Indeed, a body of evidence has already early indicated that ANXA2 may function in promoting angiogenesis in the tumor, retinal, corneal, and brain tissues." (PMID 34400908, 2021). "Furthermore, it is reported that ANXA2 plays an important role in biological behaviors involving cytoskeleton, cell phenotype and other changes in cell malignant transformation, tumor growth, tumor cell adhesion and metastasis." (PMID 33658625, 2021).
tumor (continued). "The clinical parameters between the positive and negative ANXA2 groups were compared and the results indicated that there were differences of TNM stage, tumor differentiation and lymph node metastasis between the two groups and ANXA2 expression may be correlated with these features(P < 0.05)." (PMID 33658625, 2021). "In addition, AnxA2 may facilitate the recruitment of pro-angiogenic inflammatory cells into the tumor microenvironment, which may in turn promote tumor progression." (PMID 32575495, 2020). "Thus, the expression and/or localization of ANXA2 could be driving the tumor cells to the bone niche favoring their homing to this second site and, in turn, promoting the activation of osteoclasts, altering bone homeostasis." (PMID 32197509, 2020). "Thus, we examined whether Lm-ANXA2 can augment the anti-tumor activity of PD-1 inhibitor therapy in the PDAC hemispleen model providing additional benefit if used in combination." (PMID 31113479, 2019). "Because ANXA2 is a functionally relevant protein, specifically in tumor cells with a high metastatic potential, it is conceivable that PDAC tumor cells would not be able to evade antitumor T cell immunity through antigen loss if ANXA2 is the antigen used for a Listeria-based immunotherapy." (PMID 31113479, 2019). "Moreover, inhibition of ANXA2 can suppress tumor cell proliferation, survival and metastasis." (PMID 30081903, 2018). "Interestingly, ANXA2 exhibited two distinct staining patterns in secondary tumours." (PMID 30050103, 2018). "Finally, we assayed the correlation between UBAP2 and Annexin A2 in tumor tissues." (PMID 27121050, 2016). "As a co-receptor of tissue plasminogen activator and plasminogen, ANXA2 promotes the formation and activation of plasmin and the downstream matrix metalloproteinases, and promotes extracellular matrix remodeling, angiogenesis, invasion, and metastasis of tumor cells." (PMID 26362938, 2015). "However, according to our observations, tumor cells can trigger NF-κB signaling through intracellular ANXA2 and may escape apoptosis by inducing the expression of anti-apoptotic proteins." (PMID 25611381, 2015). "The growth and volume of xenograft tumours in vivo was significantly suppressed (P<0.05) in the shRNA group compared with that of the mock group, indicating that ANXA2 may be a novel and useful target for elucidating molecular mechanisms involving the proliferation and metastasis of HCC." (PMID 24348815, 2014). "However, the growth impairment of the annexin A2-depleted tumours could be rescued by the administration of the antioxidant compound, N-acetyl cysteine (NAC), in the mice." (PMID 23434659, 2013). "Increased expression of ANXA2 has been described in a large number of spontaneous neoplasms, including pancreatic cancer, gastric carcinoma, colorectal cancer, breast cancer, high-grade gliomas and kidney cancer and is positively correlated with tumor invasion and migration." (PMID 23950866, 2013). "Interestingly, the up-regulation of annexin A2 in RCC is not limited to primary tumor sites." (PMID 23519104, 2013). "Previous studies have reported upregulation of ANXA2 and HIF1A in MM, whereas MAST4 exhibits tumor-suppressive downregulation." (PMID 41403951, 2025). "Key plasminogen receptors, including annexin A2, S100A10, alpha-enolase (ENO1), are detected in tumor-derived vesicles, and histone H2B in tumor-derived EVs for systemic transport to distant organs." (PMID 41463352, 2025). "Recent studies have demonstrated that S100A10 interacts with annexin A2 (ANXA2) to activate the mTOR pathway, thereby promoting tumor glycolysis and driving malignant tumor progression." (PMID 41195005, 2025). "They discovered that exosomal annexin A2 (AnxA2) was significantly upregulated in the serum of TNBC patients and correlated with tumour grade and poor survival." (PMID 40032646, 2025). "Binds Annexin A2/p65 to activate NF-κB, upregulating SLC38A2/SLC7A5 to enhance glutamine uptake in tumor cells." (PMID 41409273, 2025).
tumor (continued). "ANXA2, as a Vγ8Vδ3 TCR ligand, is exposed on the membrane under tumour stress, activating Vδ2neg γδ T-cells to mediate immune surveillance, suggesting ANXA2 as a potential immunotherapy target." (PMID 40234383, 2025). "Some DEGs like FREM2, ANXA2 and GPC4 revealed common enrichment in LE/IT tumor regions across GBM patient samples compared to the overall downregulation of the OPC/OL marker MBP, the neural marker NTRK2, and the ECM glycoprotein EDIL3." (PMID 41366031, 2025). "The findings revealed that C1 CALR+MCs, C2 ALOX5+MCs, C3 ANXA2+MCs, C5 IL32+MCs, myeloid cells, fibroblasts, and SMCs are capable of targeting tumor cells by releasing TWEAK." (PMID 39224598, 2024). "Mechanically, hsa_circ_0013561 increases the expression of Annexin A2 (ANXA2) by regulating miR-23b-3p competitively, resulting in epithelial-mesenchymal transition (EMT) and tumor progression." (PMID 38102461, 2024). "miR-206 acts as a tumor suppressor in PC and was found to inhibit both the KRAS and ANXA2 oncogenes." (PMID 38130990, 2023). "Studies have found that Annexin A2 (anx2) is related to tumor migration, epithelial mesenchymal transformation (EMT) and promotes tumor progression." (PMID 38114725, 2023). "Aside from ANXA2 and ANXA6, other ANXA family proteins can be used as markers of tumour occurrence and development as they affect a variety of signal pathways, such as cancer cell invasion, migration, apoptosis and autophagy." (PMID 36936694, 2023). "There is substantial evidence to show that the efficacy of CTX is related to its ability to cross the BBB as well as its high tumor-binding function mediated by the molecular targets namely, chloride channels, MMP-2, annexin A2, and recently, ERα and NRP-1." (PMID 37444498, 2023). "We postulated that peptides that target ANXA2 would presumably allow selective homing to membrane‐bound ANXA2 in the PAAD mouse model, because of the low levels of ANXA2 in non‐tumor tissues." (PMID 36453020, 2023). "Tyr23 Phosphorylation of ANXA2 by Src tyrosine kinase is an important post-translational modification of ANXA2, and p-ANXA2 has significant effects on ERK signal activation, EMT, and metastasis in tumor cells." (PMID 36229838, 2022). "As a receptor for plasminogen and tPA, ANXA2 promotes plasmin generation, resulting in degradation of extracellular matrix (ECM), which facilitates cellular migration, tumor cell invasion and neoangiogenesis." (PMID 36120574, 2022). "Preliminary studies have shown that targeting overexpressed molecules like mucin 16 (MUC16), annexin 2 (ANXA2), and also HER2 can sustain high tumor cells toxicity, and so dwindle tumor burden." (PMID 35093187, 2022). "ANXA2 belongs to the calcium-conducting annexin family, which has been reported to activate MAPK signaling and promote metastasis in tumor cells." (PMID 36229838, 2022). "Proximal tubular expression of ANXA2 in fetal kidneys was more profound at earlier gestational weeks, and similar pattern was observed in the clear cell RCC with higher grade in tumor progression." (PMID 36120574, 2022). "This analysis confirms that high mRNA expression of AnxA2 in tumor tissues results in poor survival in BLCA patients and suggests AnxA2 as a potential prognostic predictor of BLCA patients." (PMID 36428758, 2022). "The present study showed that ANXA2 positively expressed in most OSCC tissues, and was correlated with the TNM stage, tumor differentiation and lymph node metastasis in OSCC." (PMID 33658625, 2021). "Western blot was used to detect ANXA2 expression in LUAD tissues and adjacent non-tumor tissues, the transfection efficiency of SiANXA2#2 in cells and the role of ANXA2 as an upstream regulator in the AKT/cofilin signaling pathway." (PMID 34120429, 2021).
tumor (continued). "Both the ANXA2 and GPC1 mRNA levels were significantly overexpressed in the tumor tissues compared with the corresponding peritumoral tissues (P < 0.001)." (PMID 33712571, 2021). "ANXA2 and GPC1 proteins were both primarily located on the cell membrane and in the cytoplasm of tumor cells." (PMID 33712571, 2021). "The expression levels of ANXA2, ANXA3, ANXA4, ANXA8, and ANXA9 were significantly increased in tumor tissues compared with normal tissues." (PMID 34484309, 2021). "For example, in bladder cancer (BC), NUDT21 regulates the expression of ANXA2 and LIMK2 in the Wnt/β-catenin and NF-κB signaling pathways and inhibits tumor progression." (PMID 33526057, 2021). "In BC tumor tissues, downregulation of NUDT21 promotes the production of ANXA2 and LIMK2 transcripts with longer 3’UTRs, thereby reducing the expression of ANXA2 and LIMK2." (PMID 33526057, 2021). "The reduction in ANXA2 and LIMK2 expression inhibits the NF-κB and Wnt/β-catenin signaling pathways and thus promotes BC tumor progression." (PMID 33526057, 2021). "BLZ-100 is a tumor-targeted imaging agent composed of ICG and the modified CTX peptide, which targets Annexin A2 on cancer cells." (PMID 32185134, 2020). "S100A10 activated the mTOR pathway by interacting with annexin A2 (ANXA2) to accelerate tumor glycolysis, resulting in tumor malignant progression." (PMID 33324631, 2020). "In a proposed model for tumor cells, activation of receptor-bound-pro-CTSB (AnxA2/CTSB) at the caveolae triggers the uPA/plasminogen/plasmin proteolytic cascade that culminates with MMP activation and ECM breakdown." (PMID 33379277, 2020). "Further, we uncovered a significant relationship between ANXA2 and OSMR expression in clinical GBM specimens, and demonstrated their correlation with tumor histopathology and patient prognosis." (PMID 32248843, 2020). "Further, this work provided a four molecular pathway foundation (ANXA2/HMGA1/POU3F1; NFRSF13/GSN; TMOD3/RAI14/VWF; PLAT/PLAU) behind HO-1 regulation of tumor cytoskeletal cell compartments." (PMID 32197509, 2020). "We have established a four molecular pathway foundation (ANXA2/HMGA1/POU3F1; NFRSF13/GSN; TMOD3/RAI14/VWF; PLAT/PLAU) behind HO-1 regulation of the tumor cytoskeletal compartments." (PMID 32640729, 2020). "Literature evidences that ANXA2/ANXA2R exerts an important role both in the bone physiology and in the growth of tumor cells in the skeletal tissue." (PMID 32197509, 2020). "Genes ASPH, HSPB1, SQSTM1, ANXA2, and GSN (Cluster A) and PURA and MX1 (Cluster B) were downregulated for both datasets in PCa tissue vs. normal gland or normal adjacent to tumor tissue." (PMID 32640729, 2020). "Tumour Thrombospondin-1 (THBS1), Annexin II (ANXA2) and PDGFB were found to have the highest connectivity with genes of the stromal compartment." (PMID 30850588, 2019). "We characterized NUDT21-regulated genes with shortened 3′-UTRs, and found that ANXA2 and LIMK2 contribute to NUDT21-mediated tumor suppression by augmenting Wnt and NF-κB signaling." (PMID 31695759, 2019). "We identified a novel redox regulatory protein, annexin A2 (ANXA2) that plays a key role in protecting cells from ROS induced death, supporting both tumor growth and chemo-resistance." (PMID 30959964, 2019). "Aptamers have been used to detect a variety of cancers by targeting tumor markers, such as nucleolin, tenascin, prostate-specific membrane antigen (PSMA), MUC1, annexin A2, and matrix metalloprotease-9 (MMP-9)." (PMID 29301363, 2018).
tumor (continued). "Aberrantly expressed ANXA2 is observed in a wide range of malignancies, including ESCC, and plays pivotal roles in tumor formation and progression by modulating cell proliferation, apoptosis, adhesion, invasion, metastasis, and tumor neovascularization." (PMID 30081903, 2018). "It has already been shown that ANXA2 can activate STAT3 in macrophages and promote tumour formation." (PMID 30050103, 2018). "Annexin A2 (ANXA2), is a calcium-dependent phospholipid binding protein involved in the progression and metastasis of a number of tumours and is shown to interact and translocate to the nucleus in a complex with p50." (PMID 30205516, 2018). "Using Annexin A2 shRNA vectors to establish Annexin A2 stably knockdown A549/DDP cells, we further investigated the effects of Annexin A2 knockdown on cisplatin resistance in a xenograft tumor model." (PMID 28886730, 2017). "Here we show that ANXA2 is over-expressed in GBM and positively correlates with tumor aggressiveness and patient survival." (PMID 27429043, 2016). "The integration from our omics-based research provides a four molecular pathway foundation (ANXA2/HMGA1/POU3F1; NFRSF13/GSN; TMOD3/RAI14/VWF; and PLAT/PLAU) behind HO-1 regulation of tumor cytoskeletal cell compartments." (PMID 28032857, 2016). "We also identified abundant expression of proteins involved in angiogenesis (ANXA2, CA2, ATP5B and HSPB1) in MDCKYBX1 tumours." (PMID 25980435, 2015). "Keratin-31, vimentin, prohibitin, etc., were up-regulated in tumour stroma; Rho GDP dissociation inhibitor (GDI) β, superoxide dismutase, keratin-19, and annexin-A2 were down-regulated in tumour stroma." (PMID 26184160, 2015). "Recent studies showed that upregulation of ANXA2 expression activates the MAPK signaling pathway and promotes the malignant biological behaviors of tumor cells, such as proliferation, invasion and metastasis." (PMID 25362534, 2014). "Combined the experimental data in the urine and in tumor tissues collected from patients with UTUC, the crucial over-expressed proteins are calreticulin, annexin A2, and annexin A3." (PMID 24884814, 2014). "The data on the urine and tumor tissues obtained from UTUC patients which were discovered and verified by proteomic and immunological analysis strongly suggested that CALR, annexin A2 and annexin A3 are essential proteins secreted from UTUC tumor tissues." (PMID 24884814, 2014). "Data have shown that ANXA2 is involved in microvesicle trafficking and that CD147-harboring microvesicles play an important role in tumor-stroma cross-talk by stimulating the production of MMPs." (PMID 23950866, 2013). "Hypoxia-inducible factor-1α (HIF-1α), a master transcriptional regulator of oxygen-sensitive genes, is overexpressed in hypoxic tumours and increases the transcription of several genes, including VEGF and anxA2." (PMID 23555942, 2013). "Further investigation revealed that the expression of ANXA2 in HCC cells affected the shedding of CD147-harboring membrane microvesicles, acting as a vehicle for CD147 in tumor-stromal interactions and thereby regulating the production of MMP-2 by fibroblasts." (PMID 23950866, 2013). "All antigens, and particularly EZR, VCL, VIM, PDC6I, hnRNPL and ANXA2 induced a specific antibody response in KC and KPC already at 1 to 3 months of age, when the tumor stage was limited to early PanIN." (PMID 24010981, 2013). "To determine the role of AnxA2 in cell migration of JIMT-1 cells, we used lentiviral delivery of sh-AnxA2 and vector control followed by tumor biocoat migration assay." (PMID 22957061, 2012). "Additional studies are needed to furtherelucidate the mechanisms by which ANXA2 interacts with PDA stroma at both theprimary and metastatic tumor sites to accomplish these processes." (PMID 21572519, 2011). "The ANXA2 depleted and control cells were injected subcutaneously into the right flank of NOD-SCID mice and tumor growth was monitored by caliper measurement." (PMID 22185818, 2011).